IL10 (interleukin 10)
Diseases named in the same sentence as IL10 in open-access papers (continued):
Sharing a sentence is not in itself a finding about the gene and the disease.
infection (continued). "We demonstrate that IL-27 is critical for the induction of peripheral IL-10+CD4+ T cell responses and subsequent suppression of TH1 responses during the persistent phase of infection." (PMID 27926930, 2016). "There were significant differences in the levels of IFN-α, IFN-γ, IL-6, IL-7, IL-8, IL-10, IL-12p70, IP-10, MCP-1, sCD40L and VEGF in patients with DI, DW or SD infections." (PMID 26982706, 2016). "We speculate that CNS infection/inflammation can also increase CSF IL-10, a well-known inhibitory cytokine, which presumably results from immune cell secretion as a feedback response to pro-inflammatory cytokines, including IL-6, in the presence of infection/inflammation." (PMID 27924864, 2016). "On the other hand, the number of IL-10-producing CD8+ T-cells was similar between the La and Lb infection at 4 and 8 weeks PI, and it decreased throughout the evolution of the infection." (PMID 27073297, 2016). "Also importantly, the accelerated and amplified IL-10 production during rechallenge did not cause generalized immune inhibition during infection, as innate and adaptive responses were increased during the early phases of secondary infection compared with primary infection." (PMID 27630165, 2016). "To determine the cellular source of the infection-induced IFN-γ and IL-10 in the lung, we performed ex vivo culture stimulations of lung cells to characterize cytokine expression by key cell populations." (PMID 26644379, 2016). "Upon infection with Lm, we demonstrated that these preCD8α Clec9A+ DCs are endowed with regulatory properties that control the CD8+ T cell response through IL-10." (PMID 27074026, 2016). "The results demonstrate that the level of mRNA expression of IL-6, IL-8, IL-10, COX-2, IL-1β, IL-18, and TNF-α were significantly upregulated in peripheral blood monocytes following infection with H. parasuis for 3 or 6 h (p < 0.01)." (PMID 27502767, 2016). "Among the well-known Th2 cytokines, the expression of IL6, IL10 and IL13 was upregulated by infection in both breeds." (PMID 27197554, 2016). "The site of infection also showed decreased inflammatory infiltrates and decreased cytokine expressions for IL-12, TNF-α, TGF-β and IL-10." (PMID 27579922, 2016). "West and colleagues suggested that murine pulmonary infection induced by inhalation of B. pseudomallei leads to increases in IFN-γ, IL-10, IL-1β, IL-6, KC and TNF-α in the lung 1 day after infection." (PMID 27529172, 2016). "Our data can further help explain the tissue restriction of IL-10 and PDL1 expressing cells and T cell exhaustion to sites of infection or cancer induced inflammation." (PMID 26808628, 2016). "In the present studt, while NO production by spleen cells stimulated with So and Se antigens was higher at 120 days post-infection, So resulted in higher proliferations than Se, in accordance to what was observed in IFN-γ and IL-10 production." (PMID 27608632, 2016). "Following infection in both blood and spleen there was upregulation of canonical pathways including “Granulocyte Adhesion and Diapedesis”, “TREM1 Signaling” and “IL-10 Signaling”." (PMID 26918359, 2016). "Peripheral blood cDC and monocytes were assessed for IL-10 expression directly ex vivo following FMDV O1 Manisa and A24 Cruzeiro infection." (PMID 27008425, 2016). "Although CD4+YFP+ T cells were also the major source of IL-10 in the spleen during the early stages of primary infection, the numbers of splenic CD4+YFP+GFP+ T cells were significantly lower during primary infection than during secondary infection." (PMID 27630165, 2016). "However, some general points can be made: Th2-associated cytokine levels were higher overall, as might be expected given the nature of the infection; IL-3, IL-4, IL-5, IL-10 and IL-13, were all elevated in popLN cells from infected limbs, particularly so when re-stimulated with Brugia antigen." (PMID 27992545, 2016).
infection (continued). "A detailed time-course showed that, after PCV2 inoculated PAMs at a multiplicity of infection (MOI) of 0.1, 1 or 10, IL-10 secretion greatly increased in the first 8 hours, and reach in highest levels in the second 8 hours, then declined in third 8 hours." (PMID 26883107, 2016). "The level of IFNγ was similar after all infections; IL-1β was the highest in PEC after cps1-1 and in spleen after ME49; IL-17A was increased after cps1-1 and ME49 in PEC; IL-10 was increased after RH and ME49 in spleen." (PMID 27721814, 2016). "Hamster kidney following infection with virulent Leptospira, or hamster peripheral blood mononuclear cells (PBMCs) cultured with Leptospira, upregulate TNF-α, IFN-γ, IP-10, IL-10, and IL12p40." (PMID 27486445, 2016). "There was a significant increase at day 7 relative to day 5 post-infection in abundance of interleukins (IL) including IL1B, IL2, IL4, IL5, IL6, IL10 and IL13." (PMID 27311020, 2016). "Rapid and more-sustained elevations in IL-1ra, MIP-1α, IL-5, IL-10 and IL-17 levels were followed by IL-1β, IL-2, IL-7, IL-9, IL-12, IL-15, IFN-α2, MIP-1β, FGF-2 and GM-CSF at over 2 months post-infection, and accompanied by the recovery of CD4+ cells." (PMID 27830756, 2016). "The infection induced increased expression of TNF-α, IL-1β and IL-10 in both WT and SG−/− mice, but the cytokine levels were significantly lower in the SG−/− mice." (PMID 27267469, 2016). "Thirty days after treatment all interleukins levels reveal changes due to infection; while IFN-γ, IL-4, and IL-12 decreased (PC < NC), IL-10 increased (PC > NC)." (PMID 27303789, 2016). "We also detected increased levels for IL-1α, IL-4, IL-10 and M-CSF, implying that these cytokines, along with IL-12 and INF-γ, play important roles in controlling the infection and confining the chronic infection in inactive state." (PMID 27895319, 2016). "A statistically significant increase in the production of IL-10 by CD11c+ DC, was detected at 2 days post FMDV O1 Manisa infection, and was sustained until 4 days post-infection." (PMID 27008425, 2016). "Both genes have been implicated in the interaction between the anti-inflammatory cytokine interleukin 10 (IL-10) and the chemokine monocyte chemoattractant protein 1 (MCP-1) in human macrophages, influencing the establishment and persistence of infection." (PMID 27165798, 2016). "The same group also published a study about infection of hamsters with L. (V.)panamensis, where, at the site of infection, a type 1 immune response profile (IL12p40, IFN-ɣ) and type 2 (IL-10 and TGF-β) in the early and chronic phase of infection was observed." (PMID 27350537, 2016). "Unlike H5N1, H1N1 induced significantly lower levels of IL-6, MCP-1 and TNF-α at 24 h post-infection; and MCP-1, TNF-α, IL-10, IFNL1 and IFN-β at 48 h post-infection when compared with H7N9-CK or H7N9-HU." (PMID 26975414, 2016). "In the early stage of infection, STAT3 also strongly represses the production of inflammatory cytokines such as IL-6, while enhancing secretion of anti-inflammatory IL-10." (PMID 27384401, 2016). "At the infection site, few parasites remain viable thanks to the presence of CD4+ CD25+ regulatory T cells that produce IL10." (PMID 26969511, 2016). "In contrast, the increased levels of two immunosuppressive cytokines (IL-4 and IL-10) were observed during AG83+Sias infection which was declined significantly (p≤ 0.05) during AG83-Sias and UR6 infection." (PMID 27494323, 2016). "The increased ratio of IFN-γ: IL-10 producing CD4+ and CD8+ T cells in HVL after infection with LdCen1−/− and Ldp27−/− provide another correlate of protection." (PMID 27624408, 2016). "Thus, it remains to be definitively resolved, in any model, whether IL-10–producing Th1 cells have the capacity to become long-lived memory cells that subsequently regulate the nature and strength of anamnestic immune responses during secondary infections." (PMID 27630165, 2016).
infection (continued). "In this work we evaluated IFN-γ, TNF-α, IL-10, and TGF-β mRNA expression using real-time RT-PCR in 5 target tissues at 6 months and 16 months post-infection (PI) in a canine experimental model which mimics many aspects of human VL." (PMID 27171409, 2016). "To identify cytokines influenced by miR-155 and IL-10 in heart tissue, we infected B6, Mir155-/-, Il10-/-, and DKO mice with B. burgdorferi and collected hearts at 3 weeks post-infection for cytokine expression analysis." (PMID 26252010, 2015). "In fact, most of the T cell-derived IL-10 during infection was produced by FoxP3- IFN-γ+ cells, and was reflected by IL-10 secretion from E/S-stimulated LI LP cells." (PMID 25942314, 2015). "In this scenario, the infection of macrophages favors the secretion of anti-inflammatory cytokines such as IL-10 and TGF-β that impair the development of protective immune responses and favor the spread of infection." (PMID 26240832, 2015). "The frequency of these triple producers increased with the progression of the infection until day 32 post-infection, when a maximum of approximately 30% of IL-21-producing CD4+ T cells co-expressed IFN-γ and IL-10." (PMID 25763578, 2015). "We tested the developed models with MAP experimental infection data from the study of Stabel and Robbe-Austerman where calves were challenged with MAP and several immune variables were measured (IL-10, IL-4, IFN-γ and MAP CFUs." (PMID 26619346, 2015). "Serum concentration profiles (mean ± SD) for IL-2 and IL-10 cytokines in weeks 18 and 22 from E. multilocularis-infected mice treated with ABZ-CS-MPs or ABZ-T (75 mg/kg) and control, infection control groups." (PMID 26352932, 2015). "We evaluated the signaling pathways during the infection by measuring the expression of NF-κB (p65), TNF-α, IL-10 and STAT3 by Western blot analysis of hind paw supernatant of each group." (PMID 25973801, 2015). "During infection this parasite is able to induce a semi-mature phenotype of DCs which express low levels of MHCII and secrete IL-10." (PMID 26720149, 2015). "Pam3CSK4 treatment enhanced the IL-10 release from OGD-injured PC12 cells, whereas Ad-siTLR2 infection reduced the IL-10 release." (PMID 26475712, 2015). "Immunization with LiP0 was able to induce an increased expression of IFN-γ in detriment of IL-10 and TGF-β in the draining lymph node before infection creating an inhospitable environment for parasite growth." (PMID 25642946, 2015). "This differed from in vivo infection data where infected MyD88−/− and DKO mice showed similar levels of elevated serum IL-10." (PMID 26441965, 2015). "Infection of M2 macrophages with C. pneumoniae resulted in significantly enhanced release of TNF-α, IL-6, IL12p70, IL-12p40, IL-10, CCL17, and CCL24 as compared to uninfected M2 cells." (PMID 26606059, 2015). "During infection with T. gondii, L. major, or Salmonella, IL-27 is required for the generation of T-bet+CXCR3+ Treg, which produce IL-10 and limit T effector responses." (PMID 25633106, 2015). "Il1b showed modest upregulation in joints of Il10-/- and DKO mice upon infection, compared to uninfected controls, but differences between these strains and joints of infected B6 and Mir155-/- mice did not achieve statistical significance by ANOVA." (PMID 26252010, 2015). "To test the contribution of these cells to the IL-10 produced in the early phase of infection, we measured the proportions of CD4+ Foxp3− IL-10+ T cells coexpressing IFN-γ and IL-4." (PMID 26195548, 2015). "By day 4 after infection, CD4+ T cells became the predominant source of IL-10 in both 1x and 4x infected pinnae." (PMID 25974019, 2015). "Post albendazole and/or praziquantel treatment, the cellular release of IL-10, IL-33, MIP3-α/CCL20 and MIG/CXCL9 lessened significantly in all children infection groups." (PMID 25698903, 2015).
infection (continued). "Five months after infection, hamsters immunized with HIS using both immunization strategies showed an increased expression ratio of IFN-γ/IL-10 (p<0.05) suggesting a pro-inflammatory immune response." (PMID 25642946, 2015). "Conversely, five months after infection, hamsters immunized with HIS maintained a pro-inflammatory immune response (ratio IFN-γ/ IL-10) while pcDNA-LiP0 immunized hamsters continued showing a balanced cytokine profile of pro and anti-inflammatory cytokines." (PMID 25642946, 2015). "IL-10, IP-10 and RANTES are thus probably implied in the control of the pro- and anti-inflammatory balance, a key factor during PAM for limiting both infection and foetus damages." (PMID 26385579, 2015). "L. major amastigotes can modulate the signaling pathway downstream of membrane CD40 engagement by inducing ERK1/2 and IL-10 production, which inhibits the p38MAPK/IL12 pathway resulting in replication of parasite and persistence of infection." (PMID 26488744, 2015). "However, recently, Silva and colleagues reported an increase in IL-10 production by Treg cells in the spleens of dogs naturally infected with L. infantum and suggested that this could be due to persistent immune activation triggered by the infection process." (PMID 26465878, 2015). "In summary, we demonstrate that repeated exposures of the skin to infective S. mansoni cercariae leads to an early increase in IL-10 production by S. mansoni specific CD4+ T cells in the dermis, with a putative Th2 bias, at the site of infection." (PMID 25974019, 2015). "The cytokine profile (IL-10, IL-6, TNF-α) elicited upon infection with N. gonorrhoeae correlates well with the M2b-MФ phenotype." (PMID 26125939, 2015). "In this study, primers for quantitative real time PCR for Saimiri IFNγ, TNFα, IL2, IL6, IL10, and IL12 were validated and used in a study of splenic responses in S. sciureus during blood infection by P. falciparum." (PMID 25890318, 2015). "At the experimental endpoint on day 114 post-infection, IN-immunised hamsters that were considered protected expressed IFN-γ and IL10 mRNA levels that returned to uninfected skin levels." (PMID 25569338, 2015). "Results showed that serum IL-10 in carrier cattle infected with FMD virus type O (n = 4) was detected and peaked at 1 or 2 days post infection and rapidly declined thereafter." (PMID 26582423, 2015). "Tnfa was modestly elevated in hearts of Il10-/- mice, compared to the other three strains (although Tnfa was also upregulated in DKO hearts upon infection, compared to uninfected DKO hearts)." (PMID 26252010, 2015). "The correlation analysis revealed a significant correlation between LBP and CRP at 6 h (P <0.001), 12 h (P = 0.003) and 3 d (P <0.001), IL-10 and IL-6 at 7 d (P <0.001), and IL-6 and CRP at 7 d (P = 0.001) in patients with infection." (PMID 25613713, 2015). "During infection, this parasite is able to induce a semi-mature phenotype of DCs expressing low levels of MHCII and secrete IL-10." (PMID 26720149, 2015). "At the same time we detected a greater reduction of IL-17 and the regulatory TGF-β and IL-10 cytokines in the CD43+ T cell subsets, suggesting a role of CD43+ T cells in inflammatory responses during infection." (PMID 25874567, 2015). "Eighteen cytokines were elevated >2-fold relative to controls at 12 weeks of infection, including CD 30L, Fas ligand, Fractalkine, GCSF, IFN-γ, IL1-β, IL4, IL10, IL12p40/p70, IL12p70, IL17, I-TAC, Lymphotactin, MCP-1, MCSF, MIG, MIP-1α, and TIMP-2." (PMID 26079509, 2015). "Gp120 is shed from the mature virion in vitro, has been detected in the plasma of patients early during the infection and correlated with higher levels of TNF-α, IL-6, IL-10, INF-α, and IFN-γ." (PMID 25309527, 2014). "At the time of infection, mice immunized with the more protective pcDNA-mGMCSF-LdPxn1 antigen had a IFN-γ to IL-10 ratio of 4- and 11-fold higher than mice immunized with the less protective pcDNA-LdPxn1 and non-protective controls, respectively." (PMID 25500571, 2014).
infection (continued). "In this context, the ratios between IL-12/IL-4 and IL-12/IL-10, and between IFN-γ/IL-4 and IFN-γ/IL-10, indicated that vaccinated mice developed a Th1 response, which was maintained after infection." (PMID 25333662, 2014). "In contrast to TS mice, the low level of pleiotropic cytokines like IL-6 (seen here) and regulatory cytokines like IL-10 in TR mice may be pointed as a mechanism responsible for these lesions and render them unable to counteract the inflammatory effect induced by the infection." (PMID 25437299, 2014). "Interestingly, a murine study showed that infection with intestinal helminths (Heligmosomoides polygyrus) prior to sensitization and challenge with peanut extract per oral indeed significantly reduced peanut-specific IgE levels and diminished systemic anaphylactic symptoms via IL-10 production." (PMID 25002754, 2014). "The severe infection group had significantly lower levels of IFN-γ, IL-4, IL-10, IL-15, and IFN-α2 during the CP than during the AP." (PMID 24646014, 2014). "Consistent with this strong anti-inflammatory response, the regulatory cytokines IL-10 and TGF-β4 were up-regulated, being statistically significant at most time-points post-infection." (PMID 24524463, 2014). "We analyzed the concentrations of the cytokines IL-12p70, IL-12p40, IL-10, IL-6 and TNF-α in supernatants of BMDC 48 hours after infection with L. major promastigotes, or stimulation with LmAg." (PMID 25255101, 2014). "The transient increases of pulmonary TNF-α 2 days post infection for BJ501 and of INF-γ and IL-10 at 6 days post infection for PR8 were observed." (PMID 24725777, 2014). "After 5 days of infection, however, plasma levels TNF-α, monocyte chemo attractive protein (MCP)-1, IL-6, IL-10 and IL-12 were markedly elevated in all WT mice." (PMID 25115174, 2014). "S.b-B also modified the host immune response to the primary infection by increasing IFN-γ gene expression and reducing IL-10 gene expression in the small intestine." (PMID 25118595, 2014). "In our study, piglets challenged with HP-PRRSV alone developed high levels of IL-10, which indicated that IL-10 also inhibits the cell-mediated immunity and keeps the longer duration of viremia in HP-PRRSV infection." (PMID 24507659, 2014). "The presence of 33 nm AgNPs at infection led to significantly up-regulated TNF-α, IL-10, CCL2 and down-regulated IL-6 production (p≤0.05), while 46 nm AgNPs significantly down-regulated TNF-α and IL-6 (p≤0.05)." (PMID 25117537, 2014). "The two vaccinated macaques that picked the infection had slightly low titers of antibodies and their PBMC secreted high levels of IL-10." (PMID 25401783, 2014). "IL-10+ regulatory B (Bregs), CD4+Foxp3+ regulatory T (Tregs), and CD4+CXCR5+Foxp3+ follicular regulatory T (TFR) cells regulate the progression of infection disease." (PMID 25199644, 2014). "Infection induces PKR activation and expression that correlates with increased expression of IL-10 and is necessary for optimal parasite growth." (PMID 24732131, 2014). "The number of intracellular WT L. major parasites was unchanged 24 h after infection of the RAW cells and was unaffected by treatment with antibodies to TNF-α or IL-10." (PMID 24732131, 2014). "Otherwise, in the PR8 infection group, IFN-γ, and IL-10 transiently increased at days 6 post infection, and then both decreased to control level in the late stage of infections." (PMID 24725777, 2014). "As IL-10 and IFN-γ responses have been shown to play a key role in Salmonella clearance during infection, the levels of transcription of these cytokines were evaluated along the GIT." (PMID 25118595, 2014). "The frequency of IL-10-producing B cells directly correlated with viral load and inversely correlated with HIV-1-specific T cell proliferation in early infection." (PMID 24586620, 2014). "Here, in vitro infection showed that both isolates induced a strong production of NO and the cytokines TNF-α, IL-6, IL-1α, IL-1β, and IL-10." (PMID 24886263, 2014).